LGALS13 (galectin 13)
Description:
Binds beta-galactoside and lactose. Strong inducer of T-cell apoptosis. Has hemagglutinating activity towards chicken erythrocytes. Acts as an activator of ferroptosis: secreted by ferroptotic cells and acts by reducing localization of SLC7A11 at the plasma membrane.
Synonyms: PP13; PLAC8; GAL13
Tractability: No criterion of Open Targets' tractability assessment is met for any kind of drug.
Gene: Protein-coding gene on chromosome 19 (39,602,524 to 39,607,474, forward strand). Ensembl gene ENSG00000105198.
Subcellular location: Cytoplasm; Nucleus matrix; Secreted
Subcellular location (Human Protein Atlas): Nucleoplasm
Gene Ontology:
Molecular function: protein binding; carbohydrate binding; phosphatidylcholine lysophospholipase activity
Biological process: negative regulation of protein localization to plasma membrane; positive regulation of ferroptosis; phospholipid metabolic process; positive regulation of programmed cell death
Cellular component: cytoplasm; extracellular region; nuclear matrix; nucleoplasm
Genetic constraint (gnomAD): Loss-of-function variants: 13 observed, 14.4 expected, observed/expected ratio (o/e) 0.9, 90% interval 0.59 to 1.43. The upper end of that interval is the gene's LOEUF score, 1.43, which puts it in group 5 of 6, group 1 being the genes least tolerant of losing a copy. Missense variants: 171 observed, 174.37 expected, observed/expected ratio (o/e) 0.98, 90% interval 0.87 to 1.11. Synonymous variants: 68 observed, 62.39 expected, observed/expected ratio (o/e) 1.09, 90% interval 0.89 to 1.33.
Homologues: Orthologues: chimpanzee LGALS13 (99% identical), macaque LGALS13 (95% identical), Caenorhabditis elegans lec-1 (28% identical), Caenorhabditis elegans lec-3 (28% identical), zebrafish lgals3b (26% identical), Drosophila melanogaster galectin (25% identical), zebrafish lgals9l6 (25% identical), tropical clawed frog lgals9 (24% identical), zebrafish lgals9l4 (24% identical), zebrafish lgals9l5 (24% identical), zebrafish si:dkey-95h12.2 (24% identical), zebrafish lgals9l1 (24% identical), and 24 more. Paralogues in human: LGALS16 (76% identical), LGALS14 (68% identical), CLC (55% identical), LGALS3 (28% identical), LGALS4 (28% identical), LGALS7 (27% identical), LGALS7B (27% identical), LGALS8 (26% identical), LGALS9B (22% identical), LGALS9C (22% identical), LGALS9 (22% identical), GRIFIN (19% identical), and 4 more.
Diseases named in the same sentence as LGALS13 in open-access papers:
LGALS13 is named in the same sentence as 25 diseases in open-access papers, as found by Europe PMC text mining. Sharing a sentence is not in itself a finding about the gene and the disease. The quoted sentences say what the papers report.
preeclampsia (47 papers, 2009 to 2025). Preeclampsia is a hypertensive disorder of pregnancy that is characterized by new-onset hypertension with proteinuria presenting after 20 weeks of gestation, and depending on mild or severe forms may initially present with severe headache, visual disturbances, and hyperreflexia. "Reduced levels of galectin-13 caused by genetic mutations are associated with a high risk of preeclampsia." (PMID 36873388, 2023). "Some of these pregnancy specific factors on chromosome 19q13 have been linked to preeclampsia, including the galectin LGALS13 (PP13), a putative early pregnancy biomarker for placental dysfunction." (PMID 36114567, 2022). "The placental expressions of galectin-1 and galectin-13 were decreased in early pregnancy loss and preeclampsia, whereas the expressions of galectin-3 and galectin-9 were increased in preeclampsia." (PMID 33796532, 2021). "Two of these genes (LGALS13 and 14), expressed exclusively in human placenta, are important drivers of maternal adaptive immune response, with reductions in expression of either gene shown to be associated with an increased risk of preeclampsia." (PMID 32143403, 2020). "According to the research, galectin-13 levels in the first trimester of pregnancy, also known as placental protein-13 (PP-13), seem to correlate with the occurrence of preeclampsia." (PMID 37189444, 2023). "The release of galectin-13-positive microvesicles was proposed to aggravate placental ischemic stress during preeclampsia." (PMID 36873388, 2023). "Placental specific galectin-13 is a well-studied protein that has a role in damage signalling as it is elevated with the onset of preeclampsia." (PMID 36311252, 2022). "Functional enrichment analysis of the 447 human-upregulated DEGs, including ADAM12, ERVW-1, KISS1, LGALS13, PAPPA2, PGF, and SIGLEC6, revealed over-representation of genes implicated in preeclampsia and other pregnancy disorders." (PMID 34154587, 2021). "Second, galectins-13, -14, and -16 are strongly expressed in terminally differentiated syncytiotrophoblasts versus very low expression in cytotrophoblasts and the placental expression of galectin-13 and galectin-14 is decreased in women with preeclampsia." (PMID 32731422, 2020). "Low galectin-13 levels in the third trimester are strongly correlated with preeclampsia, and low levels of galectin-13 expression in week 11 were observed in trophoblasts from residual samples of chorionic villus in women who later developed preeclampsia." (PMID 29950926, 2018). "It was found that in this subform of preeclampsia there is a decreased placental expression of GCM1 and ESRRG, genes encoding transcription factors that regulate trophoblastic LGALS13 expression." (PMID 25191322, 2014). "In this context, LGALS13 expression was found to be down-regulated in villous placental tissues in preeclampsia." (PMID 25191322, 2014). "A recent study has revealed the possible molecular mechanisms leading to decreased placental LGALS13 expression in women with severe preterm preeclampsia." (PMID 25191322, 2014). "In accord with the previously discussed placental LGALS13 expression data in preeclampsia, recent studies showed a lower PP13 mRNA content in the maternal blood in the first half of pregnancy in preeclampsia compared to matched controls." (PMID 25191322, 2014). "Galectin-13 (Gal-13) is predominantly produced by the syncytiotrophoblast, while laeverin is expressed on the outgrowing extravillous trophoblast, and both are thought to be biomarkers of preeclampsia." (PMID 38928055, 2024). "In parallel to its decreased placental expression, an enhanced galectin-13 shedding from the cell surface was shown to contribute to the elevated levels of serum galectin-13 during the third trimester of pregnancy in women with preterm preeclampsia." (PMID 36873388, 2023).
preeclampsia (continued). "Indeed, reduced placental expression of LGALS13 (Galectin 13), a member of the glycan-binding proteins that regulate innate and adaptive immune responses, was found in women with preeclampsia." (PMID 34150771, 2021). "Such first trimester down-regulation of placental LGALS13 expression may be one of the earliest pathological indications for the subsequent development of preeclampsia." (PMID 25191322, 2014). "Similarly, LGALS13 has been reviewed highly to have anti-inflammatory functions, which is uniquely expressed more in placental cells 37, and the decreased expression of LGALS13 in placental leads to preeclampsia." (PMID 33854625, 2021). "Indeed, mutations in the promoter and an exon of LGALS13 presumably leading to altered or non-functional protein expression are associated with a higher frequency of preeclampsia and other obstetrical syndromes, which involve immune dysregulation." (PMID 25191322, 2014). "Serum and placental samples from four groups of cases; normal term, IUGR, early-onset and late-onset preeclampsia, were analyzed for 25(OH)D vitamin D, sFLT1, PGF, LGALS13 in serum and vitamin D receptor (VDR), MAP1LC3B and BECN1 in placental tissues." (PMID 30408071, 2018). "Moreover, mutations in the promoter and in the exons of LGALS13 presumably leading to altered, misfolded or non-functional protein expression are associated with a higher frequency of preeclampsia and also other obstetrical syndromes which involve immune dysregulation." (PMID 25191322, 2014). "Notably, several HPGs associated with invasive EVTs (ADAM12, PAPPA2, PGF), and pregnancy complications such as preterm birth and preeclampsia (ADAM12, HSD17B1, KISS1, LGALS13, PAPPA2, SIGLEC6, ERVW-1), were found to be upregulated in human compared to rhesus placenta." (PMID 34154587, 2021).
gestational diabetes (4 papers, 2016 to 2024). Carbohydrate intolerance first diagnosed during pregnancy. "In the context of gestational diabetes mellitus (GDM), increased Lgals13 serum levels during the early second trimester and lower expression in trophoblast cells of the term placenta have been reported." (PMID 31231368, 2019).
Miscarriage (4 papers, 2019 to 2025). A pregnancy that ends at a stage in which the fetus is incapable of surviving on its own, defined as the spontaneous loss of a fetus before the 22th week of pregnancy. "Such research is limited for placental galectins and has not yet been performed for gal-1, therefore, further studies are warranted to explore the association of LGALS1, LGALS13, LGALS14, and LGALS16 polymorphism with miscarriage, PE, or IUGR." (PMID 40839117, 2025).
endometrioid ovarian cancer (1 paper, 2021). "However, LGALS8 and LGALS13 showed a null association with OS either in endometrioid ovarian cancer or in serous ovarian cancer." (PMID 33854625, 2021).
ovarian carcinoma (1 paper, 2021). A malignant neoplasm originating from the surface ovarian epithelium. "The mRNA expression of LGALS4, LGALS10 and LGALS13 were all significantly downregulated in the human ovarian cancer cell lines in comparison with those in normal ovarian cell line (P < 0.05)." (PMID 33854625, 2021). "Notably, the staining score of LGALS8, LGALS10 and LGALS13 in ovarian cancer tissues were 3.04±1.24, 1.26± 0.65 and 1.52 ± 0.58, respectively, which were all lower than those in normal ovarian tissues (9.04±0.84, 7.24±1.69, 8.67±0.78) (all P<0.05)." (PMID 33854625, 2021). "However, the role of LGALS13 for predicting prognosis of ovarian cancer still needs to be researched in the future mostly according to different clinicopathologic features such as tumor types, clinical stages and grades." (PMID 33854625, 2021). "Additionally, this study showed the LGALS13 expression was lower in ovarian cancer cells and tissues than that in normal ovarian cell and tissues." (PMID 33854625, 2021). "However, the predictive role of LGALS13 in tumor especially in ovarian cancer is limited." (PMID 33854625, 2021). "In total patients with ovarian cancer, LGALS4, LGALS8, LGALS10 and LGALS13 mRNA levels were related to a better OS, and LGALS1 to a worse OS." (PMID 33854625, 2021). "The protein level of LGALS1, LGALS4, LGALS8, LGALS10 and LGALS13 in ovarian cancer cell lines were all decreased compared with those in the normal ovarian cell (all P<0.05)." (PMID 33854625, 2021).
thyroid cancer (1 paper, 2023). "When the frequency of patients expressing LGALS13 in their cancer tissues was analyzed, we found elevated levels of LGALS13 in almost half of the patients with thyroid cancer." (PMID 36766779, 2023). "Among other notable findings, we found higher LGALS13 levels in lung and thyroid cancers compared to other cancer types." (PMID 36766779, 2023). "Additionally, approximately 60% and 20% of the thyroid cancer patients expressed LGALS13 and LGALS14, respectively." (PMID 36766779, 2023).
cancer (4 papers, 2020 to 2025). A tumor composed of atypical neoplastic, often pleomorphic cells that invade other tissues. "Notably, mRNA and protein expressions of LGALS4, LGALS10 and LGALS13 were decreased in cancer cells than those in normal cells (P<0.05)." (PMID 33854625, 2021).
tumor (2 papers, 2020 to 2021). "LGALS13 might be an immunoregulatory molecule and provide an immunoprivileged environment to attack tumor." (PMID 33854625, 2021).
LGALS13 also shares sentences with these, for which no sentence is quoted: intrauterine growth restriction (8 papers); HELLP syndrome (3); Hypertension (3); Obesity (2); asthma (1); avian influenza (1); breast carcinoma (1); Cardiovascular Diseases (1); diabetes (1); endothelial dysfunction (1); gastric cancer (1); HIV-1 infection (1); infection (1); malaria (1); pregnancy disorder (1); serous ovarian cancer (1); virus infections (1).